MED1 (mediator complex subunit 1)
Diseases named in the same sentence as MED1 in open-access papers (continued):
Sharing a sentence is not in itself a finding about the gene and the disease.
atherosclerosis (4 papers, 2018 to 2024). A disease characterized by the build-up of fatty material and calcium deposition in the arterial wall resulting in partial or complete occlusion of the arterial lumen. "Similar with condition of atherosclerosis and macrophages stimulated with LPS in vitro, MED1 deletion aggravated the inflammatory response in injured common carotid arteries." (PMID 34853629, 2021). "Although our previous studies have demonstrated a protective effect of MED1 on atherosclerosis, the role of MED1 in cardiovascular disease is yet to be understood." (PMID 34853629, 2021). "Additionally, Med1 potentially mitigates atherosclerosis by promoting the polarization of macrophage M2 and suppressing the ROS generation." (PMID 38678227, 2024). "Previously, we showed that MED1 in macrophages has a protective effect on atherosclerosis; however, the effect of MED1 on intimal hyperplasia and mechanisms regulating proinflammatory cytokine production after macrophage MED1 deletion are still unknown." (PMID 34853629, 2021). "Although there are reports on the fatal effect of MED1 deletion in cardiomyocytes and the protective effect of MED1 deletion in macrophages on atherosclerosis, the role of MED1 in cardiovascular disease remains unknown." (PMID 34853629, 2021).
bladder cancer (4 papers, 2017 to 2024). "Low expression of MED1, has also been linked to another tumour type bladder cancer, and is associated with lymph node metastasis." (PMID 37525498, 2023).
breast tumors (4 papers, 2015 to 2024). "Additionally, the upregulated MED1 gene, earlier reported in association with metastasis and therapy resistance in breast tumors, was uncovered as a relevant gene in a network enriched for genes in the categories of Cellular Growth and Proliferation and Hematological System Development and Function." (PMID 25391423, 2015). "Adiponectin administration in breast tumor-bearing mice exposed to leptin results in reduced Med1 expression in breast tumors indicating that strategies to elevate adiponectin level in obese state can be beneficial." (PMID 34389732, 2021). "Taken together, these results support Jab1 as a direct downstream transcriptional target of MED1 in HER2+ breast tumors that can also reciprocally regulate MED1 ubiquitination and cyclic promoter recruitment." (PMID 33691110, 2021). "Indeed, breast tumors developed in obese hyperleptinemic mice treated with Honokiol, a bioactive compound isolated from Magnolia plants, exhibit reduced Med1 expression." (PMID 34389732, 2021). "Taken together, these results support that Jab1 is a key MED1 downstream direct target gene that plays critical roles in metastasis and CSC maintenance of HER2+ breast tumors." (PMID 33691110, 2021). "Moreover, our analyses of clinical samples further found high nuclear Jab1 and MED1 signals and their positive correlation in HER2+ breast tumor tissues." (PMID 33691110, 2021).
colon cancer (4 papers, 2016 to 2023). "Interestingly, prolonged treatment of colon cancer cells with cisplatin led to the loss of MED1 from super-enhancer-associated transcriptional condensates causing their dissolution." (PMID 37164156, 2023). "In addition to colon cancer-associated mutations, PPARγ R280C and R288C found in uterine and skin cancers reduced the transcriptional activity of PPARγ and resulted in remarkably weak binding affinities for RXRα and MED1 co-activators." (PMID 33266062, 2020).
heart failure (4 papers, 2014 to 2018). Inability of the heart to pump blood at an adequate rate to meet tissue metabolic requirements. "These values suggest poor contractility of Med1 null hearts in TmcsMed1-/- mice and support the conclusion that Med1 deficient mice die of heart failure." (PMID 27548259, 2016). "These values suggest poor contractility of Med1 null hearts and support the conclusion that Med1 deficient mice die of heart failure." (PMID 27548259, 2016). "Mice with Cre-mediated deletion of Med1 in myocardium (csMed1-/-) die within a few days after weaning due to heart failure." (PMID 27548259, 2016). "Collectively, these observations suggest that Med1 plays a critical role in the maintenance of heart function impacting on multiple metabolic, compensatory and reparative pathways with a likely therapeutic potential in the management of heart failure." (PMID 27548259, 2016). "The major cause of death of Med1 null mouse embryos at E11.5 was likely to be due to severe cardiac failure because of non-compaction of the ventricular myocardium and the resultant ventricular dilatation." (PMID 27548259, 2016). "Recently, we demonstrated that cardiomyocyte-specific deletion of Med1 in mice during late gestation, early postnatal development as well as in the adult mice using inducible cardiac Med1-deletion resulted in cardiomyopathy-related dilatation and heart failure." (PMID 30469494, 2018). "To firmly establish that the lack of Med1 expression is solely responsible for all the heart abnormalities and the associated heart failure observed in csMed1-/- mice, we used tamoxifen-inducible heart-specific Cre (Myh6-MCM)/Med1fl/fl mouse model (TmcsMed1-/-)." (PMID 27548259, 2016). "The predicted targets of miR-532-5p were Med1, NFATfatc1, and RBM20, which were reported to play crucial roles in the pathogenesis of heart failure." (PMID 29147650, 2017). "We recently noted that mice lacking cardiac-specific expression of Mediator subunit 1 (Med1), a key subunit of the mammalian Mediator complex, manifest dilated cardiomyopathy and heart failure." (PMID 30469494, 2018).
liver cancer (4 papers, 2018 to 2023). An epithelial or non-epithelial malignant neoplasm that arises from the liver. "Importantly, inhibition of p300, BRD4, CDK7 or MED1 reduces the expression of super-enhancer-associated oncogenes and exerts anticancer effects against liver cancer." (PMID 38135679, 2023). "The super-enhancer “writer” p300, super-enhancer “reader” BRD4, and super-enhancer activity regulators CDK7 and MED1 are often over-expressed in human liver cancer tissues, and their over-expression predicts poor patient prognosis." (PMID 38135679, 2023).
prostate tumor (4 papers, 2022 to 2023). "We assessed the interaction between AR and phosphorylated MED1 in clinical prostate tumor specimens (57 cases) using proximity ligation assays (PLA), and revealed that it occurred in CRPC specimens, and not in benign prostate tissues or muscles." (PMID 36535377, 2023).
viral infection (4 papers, 2014 to 2025). "Hence, prior to virus-infection, MED1’s restricted recruitment to C/I vruDEGs members can limit, but oppositely, its intensive recruitment to many C/II-III members can enhance their baseline of expression, respectively." (PMID 40131776, 2025). "Med1 and Med23 bound the viral genome with an almost identical pattern, indicating they are parts of the Mediator complex bound early during viral infection." (PMID 31638576, 2019). "Med1 also exhibited modest baseline enrichment at site L2, but exhibited no induction of recruitment in response to viral infection." (PMID 25348400, 2014).
cardiomyopathy (2 papers, 2016 to 2018). A disease of the heart muscle or myocardium proper. "Since disturbances in PPARα and PPARδ regulated FAO has been implicated in cardiomyopathy, we inferred that Med1 deletion in cardiomyocytes perturbs myocardial FAO and energy metabolism in csMed1-/- hearts." (PMID 27548259, 2016). "Furthermore, we demonstrate that cardiac specific deletion of Med1 in adult mice using tamoxifen-inducible Cre approach (TmcsMed1-/-), results in rapid development of cardiomyopathy and death within 4 weeks." (PMID 27548259, 2016). "Furthermore, in that study we showed that tamoxifen-inducible cardiac-specific deletion of Med1 led to the development of cardiomyopathy and death of mice within four weeks, thus underscoring the involvement of Med1 in regulating important cardiac-specific functions." (PMID 30469494, 2018).
dilated cardiomyopathy (2 papers, 2016 to 2019). Cardiomyopathy which is characterized by dilation and contractile dysfunction of the left and right ventricles. "Other studies have also shown that cardiomyocyte-specific ablation of the Med1 subunit of the mediator complex might cause lethal dilated cardiomyopathy." (PMID 31798643, 2019).
Ewing sarcoma (2 papers, 2019 to 2020). A small round cell tumor that lacks morphologic, immunohistochemical, and electron microscopic evidence of neuroectodermal differentiation. "Remarkably, appreciable amounts of EWS-FLI1 and EWS-ERG proteins were found in a large transcriptional complex consisting of BRD4, MED1, and RNA-Pol2 in Ewing sarcoma cells." (PMID 30903020, 2019).
ischaemia (2 papers, 2019 to 2025). "Our findings suggest that electroacupuncture may suppress Med1 expression, thereby mitigating myocardial apoptosis during ischemia–reperfusion injury." (PMID 40918160, 2025).
leukemia (2 papers, 2021 to 2023). A malignant (clonal) hematologic disorder, involving hematopoietic stem cells and characterized by the presence of primitive or atypical myeloid or lymphoid cells in the bone marrow and the blood. "In leukemia, condensates of MED1 play an important role in the E2A–PBX1‐driven gene‐specific transcriptional activation and the maintenance of leukemia." (PMID 36875159, 2023). "MED1 plays an important role in gene‐specific transcriptional activation and maintenance of leukemia." (PMID 36875159, 2023). "Med-1, a mediator of RNAPII transcription and interactor of the bromodomain protein 4 (BRD4), an SE assembly protein, was recently implicated in leukemia chemoresistance via interaction with LEDGF/p75 and in enhancing the stemness and metastasis of squamous cell carcinoma via SE formation." (PMID 34685704, 2021).
lung adenocarcinoma (2 papers, 2011 to 2017). A carcinoma that arises from the lung and is characterized by the presence of malignant glandular epithelial cells. "Further, in lung adenocarcinoma, decreased MED1 expression was associated with diverse parameters of malignancy such as advanced pT stage, positive lymphonodal status, and shorter survival." (PMID 28367434, 2017). "MED1 has been found to play an important coregulatory role in the development and progression of lung adenocarcinoma." (PMID 21306606, 2011).
non-alcoholic fatty liver disease (2 papers, 2024 to 2025). "MED1 knockout mice showed a marked alleviation of hepatic lipid accumulation without affecting other metabolic parameters, suggesting that targeting hepatic MED1 may be a strategy for treating non-alcoholic fatty liver disease (NAFLD)." (PMID 40940746, 2025).
oral squamous cell carcinoma (2 papers, 2024). "The role of Mediator complex subunit 1 (MED1), a pivotal transcriptional coactivator implicated in diverse biological pathways, remains unexplored in the context of oral squamous cell carcinoma (OSCC)." (PMID 39343952, 2024). "Our research indicates that MED1 may indirectly impact the function of CD8+ T cells within the immune microenvironment of oral squamous cell carcinoma (OSCC) through the Notch signaling pathway, in addition to its direct regulation of MMP9." (PMID 39343952, 2024). "In oral squamous cell carcinoma (OSCC), MED1, a subunit of the Mediator complex, activates the transcription of MMP-9 while simultaneously inhibiting CD8+ T-cell antitumor immune responses." (PMID 39712025, 2024).
testicular cancer (2 papers, 2016 to 2022). A primary or metastatic malignant neoplasm that affects the testis. "In testicular cancer only a single overexpression (MED15) was found; while other subunits were underexpressed (MED17, MED7, MED10, MED1)." (PMID 27050271, 2016).
ventricular dilation (2 papers, 2016 to 2021). "Reportedly, deletion of Med1 may lead to cardiac function abnormalities, including left ventricular dilation, decreased ejection fraction, and pathological ventricular remodeling." (PMID 34938340, 2021).
acute myeloid leukemia (1 paper, 2019). Acute myeloid leukemia (AML) is a group of neoplasms arising from precursor cells committed to the myeloid cell-line differentiation. "CDK8-ChIPseq in the acute myeloid leukemia (AML) cell line of MOLM-14 cells (mixed lineage leukemia fusion MLL-AF9) has found CDK8 on super-enhancers (SE) paralleled by the binding of MED1 and BRD4." (PMID 31248103, 2019).
alopecia (1 paper, 2020). Hair loss usually from the scalp. "Med1 controls epidermal lineages in skin, in which Med1 ablation in keratin 14 (Krt14) expressing epithelia enhances epidermal and sebaceous lineages while abolishing hair fate resulting in alopecia." (PMID 33255698, 2020).
bronchopulmonary dysplasia (1 paper, 2024). Bronchopulmonary dysplasia is a chronic respiratory disease that results from complications related to lung injury during the treatment of infant acute respiratory distress syndrome in low-birth-weight premature infants or from abnormal lung development in older infants. "This study aimed to predict the bronchopulmonary dysplasia (BPD) in preterm infants with a gestational age(GA) < 32 weeks utilizing clinical data, serum mediator complex subunit 1 (MED1), and serum peroxisome proliferator-activated receptor gamma coactivator-1alpha (PGC-1α)." (PMID 39069619, 2024).
chordoma (1 paper, 2023). Chordomas are rare malignant tumors arising from embryonic remnants of the notochord in axial skeleton. "Conversely, a small number of genes was identified whose gene dependency scores were of a greater magnitude in non-chordoma than in chordoma cell lines, and these genes included MED1, MRPS10, and DDX39B." (PMID 37024492, 2023).
chronic acute liver failure (1 paper, 2021). "It plays a role in the process of growth and proliferation, but the mechanism between the expression of MED1 and the regeneration of hepatocytes in patients with chronic acute liver failure has not been reported." (PMID 34612778, 2021).
ciliopathy (1 paper, 2022). A genetic disorder of the cellular cilia or the cilia anchoring structures, the basal bodies, or of ciliary function. "Eight of the 140 potential ciliopathy genes had predicted secondary interaction with gold standard cilia proteins, Aplnr, Casr, Gcgr, Grm6, Med1(or Mbd4), Mlh1, Rxfp2, and Wdr62.." (PMID 36456625, 2022). "In addition, 7 genes had primary interactions with the 24 directly interacting potential ciliopathy genes and thus had secondary interactions with known cilia proteins: Aplnr, Casr, Gcgr, Grm6, Med1(or Mbd4), Mlh1, and Rxfp2." (PMID 36456625, 2022).
co-infection (1 paper, 2013). "Next, we assessed the effect of co-infection of PIMT or its mutants along with Med1 in primary rat hepatocytes and determined glucose output as above." (PMID 24358311, 2013). "Also in co-infection of Ad/PIMT and Ad/Med1 in the presence of UO126, the glucose output was abrogated." (PMID 24358311, 2013).
endometrial cancer (1 paper, 2021). Primary or metastatic malignant neoplasm involving the endometrium (mucous membrane that lines the endometrial cavity). "Of those not previously reported in IntOGen as mutational driver genes, all were found to be expressed in their corresponding cancer types and MED1 and DOCK10 were found to be mutated at >1 in endometrial cancers." (PMID 34313788, 2021).
ependymoma (1 paper, 2025). A WHO grade II, slow growing tumor of children and young adults, usually located intraventricularly. "YAP fusion proteins nuclear condensates concentrate transcription factors and coactivators (TEAD, BRD4, MED1) and exclude polycomb repressive complex PRC2, inducing transcriptionally active chromatin loops that promote ependymoma tumorigenesis." (PMID 40507965, 2025).
esophageal squamous cell carcinoma (1 paper, 2024). Esophageal squamous cell carcinoma (ESCC) is a type of esophageal carcinoma (EC) that can affect any part of the esophagus, but is usually located in the upper or middle third. "In addition, MED1 gene has been confirmed by multiple studies to have a high mutation rate in HNSC and esophageal squamous cell carcinoma." (PMID 39343952, 2024).
head and neck squamous cell carcinoma (1 paper, 2024). A squamous cell carcinoma that arises from any of the following anatomic sites: lip and oral cavity, nasal cavity, paranasal sinuses, pharynx, larynx, and salivary glands. "The findings revealed a notable upregulation of MED1 expression in individuals diagnosed with head and neck squamous cell carcinomas (HNSC), a result further corroborated by data from the TIMER databases." (PMID 39343952, 2024).
hepatocellular carcinoma (1 paper, 2024). A malignant tumor that arises from hepatocytes. "In hepatocellular carcinoma, silencing BRD4 or MED1 repressed the transcription of SE-associated genes like SPHK1, E2F2, CCND1, MYCN, and MYC." (PMID 38443991, 2024).
Kabuki syndrome (1 paper, 2025). Kabuki syndrome (KS) is a multiple congenital anomaly syndrome characterized by typical facial features, skeletal anomalies, mild to moderate intellectual disability and postnatal growth deficiency. "In Kabuki syndrome, mutations in histone lysine methyltransferase MLL4 and demethylase UTX reduce their ability to form phase-separated condensates, impairing recruitment of MED1/BRD4 and exclusion of PRC1/2." (PMID 40507965, 2025).
liver fibrosis (1 paper, 2025). "During liver fibrosis, mediator complex subunit MED1 and epigenetic regulator BRD4 exhibit prominent LLPS activity, regulating the expression of fibrotic genes and ECM production." (PMID 41280670, 2025).
lymph node metastases (1 paper, 2017). "The presence of lymph node metastases was significantly associated with low MED1 expression in the primary tumor, whereas an association between MED1 expression and distant metastases remained non-significant probably due to low sample sizes (p = 0.07; pM1, n = 4)." (PMID 28367434, 2017).
male breast carcinoma (1 paper, 2012). A malignant neoplasm involving the male breast. "Among the other genes studied, copy number gain of MED1, PRDM14, and BIRC5 were associated with a high grade phenotype, indicating that these genes play a role in the development or progression of aggressive male breast cancer." (PMID 22527098, 2012). "Also MED1, PRDM14, MTDH, and BIRC5 seem to be important in the development or progression of high grade male breast cancer." (PMID 22527098, 2012).
myopia (1 paper, 2023). "We identified significant selection signatures in myopia-associated genes related to sunlight, including RHO, TSPAN10, and MED1, and we validated the interaction between these genes and the light environment." (PMID 37919796, 2023).
ovarian carcinoma (1 paper, 2022). A malignant neoplasm originating from the surface ovarian epithelium. "In our study, we found the signature-related genes such as AXL, FZD5, POLR3H, and MED1 were related to the immune cell expressions in ovarian cancer." (PMID 35769811, 2022). "Thus, we found that the expression of FZD5 and MED1 correlated with the age, and CCL15 correlated with lymphatic invasion in ovarian cancer." (PMID 35769811, 2022).
ovarian endometrioid carcinoma (1 paper, 2025). "WGS analyses revealed rearrangements involving PTEN, NF1, and NF2 in ovarian endometrioid carcinomas and NF1 and MED1 in ovarian mucinous carcinomas." (PMID 40981433, 2025). "Whole-genome sequencing revealed rearrangements involving PTEN, NF1, and NF2 in ovarian endometrioid carcinomas and NF1 and MED1 in ovarian mucinous carcinomas." (PMID 40981433, 2025).
ovarian mucinous carcinomas (1 paper, 2025). "MED1 rearrangements may lead to overexpression of this protein that could be exploited in patients with ovarian mucinous carcinoma." (PMID 40981433, 2025).
pseudoachondroplasia (1 paper, 2026). Pseudoachondroplasia is characterized by severe growth deficiency and deformations such as bow legs and hyperlordosis. "Some COMP mutations previously identified in pseudoachondroplasia, an allelic disorder of MED1, were shown in our study to exhibit a typical MED1 or intermediate phenotype." (PMID 42074581, 2026).